PIM1 (Pim-1 proto-oncogene, serine/threonine kinase)
Diseases named in the same sentence as PIM1 in open-access papers (continued):
Sharing a sentence is not in itself a finding about the gene and the disease.
colon carcinoma (11 papers, 2013 to 2023). "PIM1 promoted the proliferation, differentiation and cell survival of colon cancer and its inhibition has been suggested as a possible target for therapeutic intervention." (PMID 30655588, 2019). "In this study, we evaluated pim-1 expression in tumors, tumor stroma and tumor-adjacent mucosa together as an independent prognostic factor for colon cancer patients." (PMID 24116137, 2013). "In this study, four independent prognostic factors were identified for colon cancer patients: pim-1 expression in tumors, tumor stroma, tumor-adjacent mucosa, as well as tumor stage." (PMID 24116137, 2013). "However, miR-33a acts as a tumor suppressor miRNA in colon cancer by directly downregulating of the oncogene Pim-1." (PMID 26507842, 2015). "These combined characteristics of pim-1 expression in tumors, tumor stroma and tumor-adjacent mucosa suggest that pim-1 expression might serve as a useful prognostic marker for colon cancer." (PMID 24116137, 2013). "In our study of colon cancer, we found that, in contrast to pim-1-negative immune inflammatory cells, pim-1-positive immune inflammatory cells that accompany cancer-associated fibroblasts were associated with increased DFS and OS, perhaps acting as tumor-killing subclasses of immune cells." (PMID 24116137, 2013). "When PIM1 was inhibited, PIM2 expression increased across different cancer types generally, and Pim-3 was reported to be aberrantly expressed in colon cancer." (PMID 25749522, 2015). "Previous work in our lab demonstrated that PIM1 is upregulated in hypoxia, independent of HIF-1 signaling, and treatment with a small-molecule PIM inhibitor reduces tumor metastasis in orthotopic models of prostate and colon cancer." (PMID 37042842, 2023).
myeloma (11 papers, 2013 to 2025). "Pim‐1 is overexpressed in hematologic diseases and solid tumors, pim‐2 in myeloma, lymphoma, and leukemia, and pim‐3 in substantial organ tumors." (PMID 37162273, 2023). "Pim-1 and Pim-2 are frequently overexpressed in hematological malignancies, such as AML, chronic myeloid leukemia, and multiple myeloma, and implicated in their pathogenesis through various mechanisms, including upregulation of the mTORC1 pathway." (PMID 29507660, 2018). "MiR-33b was recently characterized in multiple myeloma as a tumor suppressor through targeting PIM-1, an oncogene." (PMID 24143167, 2013). "Pim‐1 activates endonucleases responsible for DNA breaking during apoptosis and inhibits DNA repair systems to promote inter‐ribosomal breaks in chromosomal DNA in several cell lines derived from mouse NS‐1 myeloma cells." (PMID 37162273, 2023). "One example is CXR-4945, a dual PIM1 and casein kinase-2 (CK2) inhibitor, which has undergone Phase I trials in adults with multiple myeloma, breast cancer, and solid tumors." (PMID 35892829, 2022). "PIM1 and PIM2 expression are correlated with hematologic malignancies, including myeloma, lymphoma, and leukemias." (PMID 35892829, 2022). "ChIP-seq assays showed that acetylation of H3K27 at cell cycle/mitochondrial gene promoters and super-enhancers of genes relevant for multiple myeloma biology (c-MYC, BCL-XL, CCND2, IRF4, MCL1, PIM1, PRDM1, and XBP1) was mildly increased in HDAC3 knockdown cells compared with nonsilencing cells." (PMID 36846090, 2022).
prostate tumors (11 papers, 2010 to 2026). "Clinical studies demonstrate a positive correlation between PIM1 expression and tumor metastasis in breast, lung, pancreatic, and prostate tumors." (PMID 37042842, 2023). "PIM1 is highly expressed in hematopoietic cells and prostate tumors, PIM2 has increased expression in lymphoid and brain tissues, and PIM3 is elevated in breast, liver, kidney, and brain tissues." (PMID 36429128, 2022). "NDRG1 is phosphorylated by PIM1 at serine 330 (pS330), and the level of NDRG1 pS330 is associated higher grade prostate tumors." (PMID 33398037, 2021). "We also found that PIM1/2 are overexpressed in a subset of human male germ cells and prostate tumors correlating with inflammatory features and stem cell markers." (PMID 27901106, 2016). "In human prostate tumors, it was also possible to detect a small subset of tumors with a clear increase in the levels of PIM1/2 transcription." (PMID 27901106, 2016). "Similarly, analysis of human breast and prostate tumors indicates that PIM1/2 overexpression correlates with inflammatory features." (PMID 36429128, 2022). "Similarly, PIM1‐mediated H19 induction was also observed in normal human prostate‐derived epithelial cells, hPrEC, or prostate tumor cell line PC3." (PMID 32146726, 2020). "This subset of tumors with high PIM1/2 constitutes approximately 15% of all prostate tumors." (PMID 27901106, 2016). "Furthermore, in human prostate tumors, coexpression of c-MYC and PIM1 is associated with higher Gleason grades." (PMID 23565217, 2013). "PIM1 levels are elevated in PCa compared to benign prostatic epithelium, with partially contrasting conclusions on whether PIM1 expression correlates with prostate tumor aggressiveness." (PMID 33932111, 2021). "We also found that PIM1 and PIM2 are overexpressed in a subset of human male germ cell and prostate tumors and that this overexpression correlated with clear inflammatory features and stem cell markers." (PMID 27901106, 2016). "We also found that PIM1 and PIM2 are overexpressed in a subset of male germ cell and prostate tumors and that this overexpression correlated with clear inflammatory features and stem cell markers." (PMID 27901106, 2016). "Our data suggest that PIM1 expression, in addition to ABI2, could serve as a potential biomarker to assess the invasive and metastatic potential of primary prostate tumors." (PMID 37042842, 2023). "Considering this information, we examined the protein levels of NDRG1 pS330, total NDRG1, and PIM1 by immunohistochemistry using tissue microarrays containing primary prostate tumors and adjacent non-cancer tissue." (PMID 33398037, 2021). "Therefore, we tested whether PIM1 and PIM2 expression is correlated with stem markers in human male germ cell and prostate tumors." (PMID 27901106, 2016).
hepatocellular carcinoma (10 papers, 2011 to 2025). A malignant tumor that arises from hepatocytes. "This evidence is based on results from six parallel sets of experiments: (a) miR‐24‐2 is associated with abnormal expression of Pim1 in human hepatoma cells." (PMID 32030886, 2020). "T3 suppressed proliferation by targeting miR-214 to downregulate PIM-1 in hepatoma cells." (PMID 29093516, 2017). "PIM1, acted as an oncogene, has been demonstrated to regulate cell cycle, EMT and metastasis in many types of cancers including melanoma, hepatocellular carcinoma and osteosarcoma." (PMID 30989585, 2019). "In the human hepatoma cell line HepG2, but not in PMs, the long form of Pim1 (Pim1L) interacts with cell-surface-resident ABCA1 (csABCA1), thereby protecting it from ubiquitination and subsequent lysosomal degradation via its phosphorylation function." (PMID 40526435, 2025). "In this study, we obtained that oleanolic acid promotes high expression of HMOX1, PIM1 and ICAM1 in hepatocellular carcinoma cells through oleanolic acid-related expression profiles, which further suggests that HMOX1, PIM1 and ICAM1 are key targets of oleanolic acid." (PMID 38127054, 2023).
melanoma (10 papers, 2013 to 2025). A malignant, usually aggressive tumor composed of atypical, neoplastic melanocytes. "Through pathway enrichment analysis, four key melanoma-associated genes (PIM1, MEK1, CDK2, and PDK1) were identified as potential therapeutic targets." (PMID 40649898, 2025). "Genetic changes of PIM-1 gene (e.g., amplifications, mutations, and deletions) are counted for about 8% of melanomas according to data of the Cancer Genome Atlas (TCGA)." (PMID 29483938, 2018). "Through literature mining, it was found that the four known melanoma-related proteins PIM1, MEK1, CDK2, and PDK1 can potentially be targets of the bioactive compounds of B. stenostachya." (PMID 40649898, 2025). "The pathway enrichment analysis revealed the four melanoma-related proteins PIM1, MEK1, CDK2, and PDK1 in several pathways including the pathways related to cancer." (PMID 40649898, 2025). "In light of these findings, it becomes clear that melanoma cells exploit a diverse range of pathways which can be targeted by the bioactive compounds of B. stenostachya, particularly PIM1, MEK1, CDK2, and PDK1." (PMID 40649898, 2025). "It is significant that the average docking scores for naringin-7-rhamnoglucoside and the melanoma-related proteins were as follows: PIM1 (−5.91897), MEK1 (−6.07004), CDK2 (−5.26133), and PDK1 (−6.29952)." (PMID 40649898, 2025). "To determine if knocking down (KD) PIM1 activity is sufficient to reduce melanoma proliferation, we used two distinct PIM1-inhibiting shRNAs." (PMID 27448973, 2016). "Given the anti-proliferative and anti-invasive effects of PIM1 KD on melanoma cells grown in vitro, we conducted in vivo studies to confirm the role of PIM1 in melanoma tumor growth." (PMID 27448973, 2016). "SM200-related anti-melanoma observations were further explored using PIM1 knockdown studies and a clinically available pan-PIM kinase inhibitor (SGI-1776)." (PMID 27448973, 2016). "While mechanisms regulating PIM kinase levels are still being unraveled, Pim1 gene expression is controlled by multiple transcription factors and pathways of relevance to melanoma." (PMID 27448973, 2016). "To further explore the effects of knocking down PIM1 in melanoma cells, we cultured the PIM1 KD cells as 3D spheroids and observed decreased invasion compared to the empty vector controls." (PMID 27448973, 2016). "To confirm PIM kinases as valid targets for melanoma patients and to assess expression variability, we stained human melanoma tissue for PIM1, PIM2, PIM3." (PMID 27448973, 2016). "Our findings suggest the benefit of inhibiting the PIM1 kinase in melanoma and also the need to investigate the contribution of the other PIM isoforms in melanoma biology." (PMID 27448973, 2016). "The highly supported results have shown that naringin-7-rhamnoglucoside from B. stenostachya could possibly target the genes involved in the progression of melanoma, specifically PIM1, MEK1, CDK2, and PDK1." (PMID 40649898, 2025). "Given that PIM1 knockdown was insufficient to completely halt melanoma cell growth and the expression of different PIM kinase isoforms was still detected, compensation mechanisms between PIM isoforms needs to be further explored especially since not all isoforms share the same effectors." (PMID 27448973, 2016). "Using knockdown studies, we showed that PIM1 contributes to melanoma cell proliferation and tumor growth in vivo; however, the presence of PIM2 and PIM3 could also influence the outcome." (PMID 27448973, 2016). "We show that PIM kinases are expressed in melanoma patients' samples and cell lines, and that PIM1 inhibition by knockdown studies or the use of a clinically available PIM kinase inhibitor can reduce proliferation, viability, and invasion in preclinical models of melanoma." (PMID 27448973, 2016).
melanoma (continued). "Since our results show that PIM1 knockdown can cause a reduction in melanoma cell proliferation and invasion (in vitro), or tumor growth in vivo, we suggest a contribution of PIM kinases to melanoma pathobiology and the possibility to inhibit such activity." (PMID 27448973, 2016). "SMI-4a, a pharmacological inhibitor of PIM-1, could decrease cell viability, induce apoptosis, and promote Caspase 3/7 activity in both A375 and G361 melanoma cells, and SMI-4a inhibited tumor growth by inducing autophagy via down-regulating AKT/mTOR axis in melanoma cells." (PMID 29483938, 2018). "In addition, the expression of AFF1, PIM1, PTPN13 and TXNIP was downregulated in UV-irradiated FM SFs with a R87P-CDKN2A mutation, and the expression of these genes was also found to be downregulated in melanoma tissue." (PMID 23371019, 2013). "Together, these findings validate the biological relevance of the added proteins, namely PIM1, MEK1, CDK2, and PDK1, in the central pathways of melanoma." (PMID 40649898, 2025). "In addition, PIM-1 could promote melanoma cells migration and invasion." (PMID 29483938, 2018). "We observed the expression of PIM1 and PIM2 in all melanoma samples, while PIM2 and PIM3 levels were most elevated in samples expressing lower PIM1 levels." (PMID 27448973, 2016). "Based on the kinome reprogramming triggered by T-RECS ASO and its significant impact on AKT1 and PIM1 activities, it is possible that jointly targeting MEK and T-RECS directly inhibits both the MAPK and AKT pathways, which are the two main drivers of therapeutic resistance and melanoma progression." (PMID 38383439, 2024).
ovarian cancer (10 papers, 2014 to 2021). A primary or metastatic malignant neoplasm involving the ovary. "GBP1 binds to proto-oncogene serine/threonine-protein kinase pim-1 (PIM1) and causes paclitaxel resistance in ovarian cancer, implying that PIM1 might interact with GBP5 for drug resistance in OSCC." (PMID 34439200, 2021). "Furthermore, preliminary experiments with small molecule-mediated inhibition of GBP1's association with PIM1 have demonstrated restoration of treatment sensitivity and reduction in ovarian cancer growth, showing that GBP1 is an excellent molecular target for combating TXR in tumor progression." (PMID 32117203, 2019). "NSC756093 is a potent in vitro inhibitor of the GBP1:PIM1 interaction and this property is maintained in vivo in ovarian cancer cells resistant to taxane." (PMID 31998647, 2019). "In human breast, endometrial and ovarian cancer, a subset of tumors showed high levels of PIM1 and PIM2 correlating with inflammatory molecules." (PMID 28938604, 2017). "Indeed, a 4-aza podophyllotoxin derivative was demonstrated to act as a potent in vitro inhibitor of the GBP1:PIM1 interaction, which is a property that is maintained in vivo in ovarian cancer cells resistant to paclitaxel." (PMID 29115931, 2017). "However, in ovarian cancer where the smaller isoform is expressed, PIM1 expression alone is not correlated with changes in RFS." (PMID 28090373, 2016).
T-cell lymphoma (9 papers, 2006 to 2022). "In this mouse model, the overexpression of a pim2 transgene in lymphoid cells predisposed mice to T-cell lymphomas that were similar to those promoted by pim1 transgenes." (PMID 24860787, 2014). "Transgenic mice over-expressing either Pim-1 or Pim-2 are predisposed to T cell lymphomas, whereas both Pim-1 and Pim-2 act synergistically with c-Myc to accelerate development of B-cell tumors." (PMID 22506047, 2012). "Similarly, mice expressing Pim1 in T-cells were more susceptible to carcinogenesis-induced T-cell lymphoma." (PMID 23565217, 2013). "Upregulation of RUNX2 and Pim-1 was found to synergistically promote the development of T-cell lymphoma, suggesting the phosphorylation mediated by Pim-1 has a positive effect on RUNX2′s cancer-promoting function." (PMID 36429115, 2022). "Overexpression of Pim-1 driven by the Eμ enhancer was shown to lead to a low incidence of T cell lymphomas and increased sensitivity to chemically induced T cell transformation." (PMID 27287229, 2016). "Pim-1 was originally identified as a target for proviral activation in Moloney murine leukemia virus induced T cell lymphomas." (PMID 27287229, 2016). "The pim1 gene was identified as a common insertion site in 50% of T-cell lymphomas that were induced by M-MuLV or AKR-MCF 247 virus." (PMID 24860787, 2014). "Pim1 was discovered as a proviral insertion site in Moloney-murine leukemia virus in T-cell lymphomas, and further studies identified the other two family members, pim2 and pim3, as alternative integration sites." (PMID 24860787, 2014). "In summary, pim1 is a very common insertion site in T-cell lymphomas that are induced by M-MLuV infection in different mouse strains." (PMID 24860787, 2014). "Eμ-Pim1 transgenic mice engineered to overexpress Pim1 in lymphocytes develop T cell lymphomas and cooperate with another proto-oncogene Myc to accelerate the disease progression." (PMID 20515470, 2010). "Several mouse strains have been used to study the proviral integration of M-MuLV; most of these studies have been carried out in the BALB/c and C57BL strains, but pim1 rearrangements were also observed in two T-cell lymphomas, one from an HRS/J mouse and one from a C58/J mouse." (PMID 24860787, 2014). "Interestingly, infection of these transgenic mice with murine leukemia virus (MuLV) promoting the integration of the provirus in the Pim-1 locus enhanced dramatically the incidence of tumors and reduced the latency of T-cell lymphoma development." (PMID 25491234, 2014). "Pim-1 was first identified as an oncogenic gene in murine T-cell lymphomas, which became activated after pro-viral insertion in the 3'UTR of the Pim-1 gene." (PMID 16403219, 2006). "In the Eμ-pim1 model only 5–10% of mice developed T-cell lymphoma, suggesting that Pim-1 alone is not able to induce a massive proliferation." (PMID 25491234, 2014).
gastric cancer (8 papers, 2014 to 2022). A primary or metastatic malignant neoplasm involving the stomach. "PIM1 is a threonine kinase often overexpressed in gastric cancers, potentially causing HB to be lower than usual." (PMID 35546387, 2022). "miR-33a directly targeted cyclin-dependent kinases 6 (CDK6), cell cycle protein D1 (CCND1), and serine/threonine kinase PIM-1, and expression was down-regulated in gastric cancer tissues and cell lines, thereby inhibiting gastric cancer cell proliferation." (PMID 35743814, 2022). "Previous studies showed that down-regulation of miR-33a promoted CDK6 and Proto-oncogene serine/threonine-protein kinase Pim-1 (PIM1) expression and induced gastric cancer cell proliferation, suggesting that miR-33a is a key regulator in cell proliferation." (PMID 32436962, 2020). "Similarly, miRNA-101-3p was reported to inhibit both proliferative and migratory capabilities of gastric carcinoma cells and enhance apoptosis via PIM-1 expression modulation." (PMID 35320929, 2021). "Additionally, upregulation of the PIM-1 oncogene may be a prognostic tumor marker for gastric cancer, as PIM-1 overexpression in gastric glands has been shown to correlate with the formation of lymph node metastases and survival." (PMID 25788990, 2015).